G6PD (glucose-6-phosphate dehydrogenase)
Diseases named in the same sentence as G6PD in open-access papers (continued):
Sharing a sentence is not in itself a finding about the gene and the disease.
liver cancer (32 papers, 2015 to 2025). An epithelial or non-epithelial malignant neoplasm that arises from the liver. "Researchers have shown that CHB infection of the human liver and HBV-related liver cancer is linked with high expression of glucose-6-phosphate dehydrogenase (G6PD), the first and rate-limiting enzyme of the pentose phosphate pathway, as well as increased Nrf2 transcription factor activity." (PMID 37946175, 2023). "G6PD is significantly upregulated in HCC patients and cell lines, and is associated with liver cancer metastasis and poor prognosis." (PMID 39980550, 2025). "Clinically significant overexpression of G6PD has been documented in multiple malignancies, including lung, renal, breast and liver cancer, and it correlates with adverse clinical outcomes." (PMID 41050691, 2025). "miR-122 and TSP50 can regulate the proliferation of liver cancer cells by modulating the expression or activity of G6PD." (PMID 39980550, 2025). "This indicates that the mechanism related to the NRF2/G6PD axis plays an important role in HBV-related liver cancer development and progression." (PMID 39859324, 2025). "Compared with the adjacent tumor tissue and most liver cancer cells lines, a significant increase expression of G6PD, CDCA8, and CTSC in HCC tissues and liver cancer cells was observed, whereas CXCL9 was significant downregulated." (PMID 38742112, 2024). "Through meticulous cell experiments, we confirmed the substantial impact of low G6PD expression on the proliferative activity, migration, and invasion of liver cancer cells." (PMID 38297250, 2024). "Our analysis consistently indicated a positive correlation between G6PD and poor prognosis in liver cancer." (PMID 39308686, 2024). "Within the constructed model, G6PD was identified as a key gene, potentially serving as a senescence-related target in liver cancer." (PMID 39383169, 2024). "Studies have suggested that direct knockout of G6PD in hepatocytes, liver cancer cells, and fibroblasts leads to a significant increase in IL-8 expression." (PMID 39621725, 2024). "In fact, G6PD is highly expressed in liver cancer cells, promotes hepatocyte proliferation and tumor formation, and negatively correlates with patient survival." (PMID 37993470, 2023). "Remarkably, analysis of miR-122 expression in TCGA LIHC cohorts indicated the inverse correlation between G6PD and miR-122 in liver cancer patients." (PMID 37627157, 2023). "They show that the expression of miR-122 is inversely correlated with G6PD expression and that G6PD mRNA levels increase in tandem with rising tumor grade in The Cancer Genome Atlas liver cancer patients." (PMID 36803831, 2023). "In order to further investigate the link between miR-122, G6PD in liver cancer development, we specifically focused on HCC patients with or without hepatitis B virus (HBV) infection." (PMID 37627157, 2023). "Conversely, the tumor suppressor gene encoding protein PTEN forms a complex with hnRNPK to inhibit its activity, and shearing of G6PD precursor RNA inhibits liver cancer." (PMID 35352475, 2022). "Collectively, these results suggested that TSP50‐mediated deacetylation of G6PD at K171 is an important tumorigenic factor in liver cancer." (PMID 33630390, 2021). "Previous studies demonstrate that PLK1-mediate the activation of phosphorylates glucose-6-phosphate dehydrogenase which is critical for the promoting the cell cycle progression and tumor growth in liver cancer and cervical cancer." (PMID 31488217, 2019). "This notion is further supported by the fact that increased G6PD levels predict a worse patient prognosis and tumor recurrence in liver cancer." (PMID 29904144, 2018). "The extensive TCGA-LIHC collection of healthy, benign tissue and liver cancer samples correlated upregulation G6PD mRNA levels with higher tumor grades." (PMID 29904144, 2018). "Our study shows that G6PD is a critical miR-122 target that is likely to modulate glucose metabolism in liver cancer." (PMID 29904144, 2018).
liver cancer (continued). "This is also reflected at the G6PD protein and RNA levels in liver cancer cells transfected with miR-1 or miR-122 mimics." (PMID 29904144, 2018). "G6PD mRNA and miR-122 levels in liver cancer patient data downloaded from TCGA were found to negatively correlate (R-squared = 0.1772, P-value = 5.874367 × 10−19, regression coefficient = −0.4696232)." (PMID 29904144, 2018). "Subsequently, we analyzed the G6PD gene expression in WRL68, LI-7, SNU-398, SNU-449, SK-HEP-1 cells, and showed that compared with normal liver cells, the G6PD expression level of liver cancer cells was significantly increased, and the expression level of LI-7 and SNU-449 was the highest." (PMID 38297250, 2024). "Since G6PD directly reduced the ratio of NADP+/NADPH which may be directly involved in the proliferation of liver cancer cells, we evaluated the effect of NADP+ on cell proliferation." (PMID 33630390, 2021). "To address whether both could contribute equally to the upregulation of G6PD expression in liver cancer, we compared miR-1 and miR-122 levels in the context of G6PD mRNA levels using density distribution plots." (PMID 29904144, 2018). "In this same dataset, we found a profound inverse correlation of miR-122 with G6PD levels in liver cancer, suggesting that miR-122 may play a regulatory role of PPP flux through G6PD suppression." (PMID 29904144, 2018). "The glucose-6-phosphate dehydrogenase (G6PDH) is a rate-limiting enzyme in the pentose phosphate pathway (PPP), which has been implicated in the regulation of cell transformation, proliferation, apoptosis and angiogenesis in several kinds of tumors, including liver cancer." (PMID 38005711, 2023). "To confirm the effect of G6PD on liver cancer cells, we transfected genOFF st-h-G6PD into LI-7 and SNU-449 liver cancer cells using transfection reagents." (PMID 38297250, 2024). "Then, we also explored the correlation between the expression of 11 ROS-related genes and TNM stages in liver cancer, and the findings showed that the expression of CDKN2D, G6PD, MSRA, OXSR1, PFKP, and STK25 was connected with TNM stages (P < 0.05)." (PMID 34795841, 2021). "While the role of G6PD in the HCC has been investigated, the role of STK25 in liver cancer is still unclear." (PMID 34795841, 2021). "Interestingly, elevated G6PD is not observed in liver cirrhosis which is a main cause of liver cancer, indicating that G6PD might play an important role in promoting malignant transformation." (PMID 32582032, 2020). "Our findings revealed significantly elevated G6PD expression levels in liver cancer tissues as compared to normal tissues." (PMID 38297250, 2024). "Our finding that TSP50 positively regulates G6PD activity adds new mechanistic insight into the regulation of PPP and suggests that modulating TSP50‐mediated G6PD activity may be a potential therapeutic strategy for liver cancer." (PMID 33630390, 2021). "Notably, G6PD, FASN and LPIN1 are upregulated in HCC compared with non-tumor livers in both HCC cohorts while ETFDH is downregulated, highlighting the likely role of lipid metabolism and PPP pathways in liver cancer." (PMID 37301960, 2023).
Obesity (32 papers, 2005 to 2025). Accumulation of substantial excess body fat. "Obesity is known to be associated with elevated activity of glucose-6-phosphate dehydrogenase (G6PD), the rate-limiting enzyme in the pentose phosphate pathway (PPP)." (PMID 39458496, 2024). "Altered G6PD activity is associated with lipid dysregulation, insulin resistance, increased body weight, and obesity since G6PD is the common player in glycolysis, gluconeogenesis, lipid metabolism PPP, and oxidative stress." (PMID 36992836, 2023). "G6PD deficiency renders macrophages resistance to LPS stimulation and attenuates insulin resistance in obesity mice through inhibition of adipose tissue inflammation." (PMID 31805953, 2019). "Bone marrow transplantation from G6PD-deficient mice to wild-type mice reduces obesity-induced inflammation in adipose tissue and improves insulin resistance." (PMID 31500396, 2019). "In high-fat-diet (HFD)-induced obesity, G6PD-deficient mice have decreased insulin and Homeostatic Model Assessment for Insulin Resistance (HOMA-IR) index." (PMID 31500396, 2019). "Therefore, we suggest that EDCs can adversely affect the G6PD activity associated with increased body weight, obesity, metabolic syndrome, and diabetes." (PMID 36992836, 2023). "In high-fat diet-induced obesity models, acetate supplementation restored the function of obestatin and glucose-6-phosphate dehydrogenase-glutathione dependent antioxidant system, thereby ameliorated obesity and hepatic lipid metabolism disorders." (PMID 40165786, 2025). "Complementary bioinformatics analysis revealed four key targets associated with obesity onset: HSD11B1, RXRG, G6PD and PIK3R1." (PMID 41032481, 2025). "Glucose-6-phosphate dehydrogenase (G6PD), a rate-limiting enzyme of the pentose phosphate pathway (PPP), has been implicated in tissue inflammation and systemic IR in obesity." (PMID 40801620, 2025). "G6PD deficiency improves IR with reduced adipose tissue inflammation in obesity; thus, G6PD levels can be used as a marker of adipocyte activity." (PMID 40801620, 2025). "Our findings suggest G6PD is a regulator of HFD-induced obesity, adipocyte hypertrophy, and fatty liver." (PMID 38876306, 2024). "Nonetheless, our findings suggest G6PD deficiency in G6PDS188F rat, at least partly, lessened inflammation of adipose tissue and decreased adipocyte size in HFD-induced obesity model." (PMID 38876306, 2024). "There was increased G6PD expression in WAT when mice were fed a high-fat diet or in genetic models of obesity." (PMID 39061889, 2024). "G6PD is a key enzyme required for lipogenesis, and its increase is closely connected to the disturbance of lipid metabolism and insulin resistance in obesity." (PMID 37299513, 2023). "In our previous study using diet-induced obesity mice, we confirmed a decrease in the mRNA expression of fatty acid synthase and glucose-6-phosphate dehydrogenase due to a reduction in SREBP-1c mRNA expression." (PMID 33396447, 2020). "In some peripheral pathological conditions (e.g. heart failure, atherosclerosis, and obesity), increased activity of G6PD promotes cellular ROS production and pro-inflammatory signaling through increased availability of NADPH to ROS-producing enzymes." (PMID 31805953, 2019). "The rate-limiting enzyme in the pentose phosphate pathway, glucose-6-phosphate dehydrogenase (G6PD), is an important mediator of adipose tissue inflammation and insulin resistance in subjects with obesity." (PMID 31212707, 2019). "G6PD can activate NF-κB in different cell types, including adipocytes in obesity and β-cells in type-two diabetes." (PMID 25945076, 2015). "The LASSO regression models were built from data from obese and normal tissues, and the λ analysis indicated that the model achieved optimal predictive accuracy for obesity at λ = 4, leading to the identification of 4 core diagnostic genes, including HSD11B1, RXRG, G6PD and PIK3R1." (PMID 41032481, 2025).
Obesity (continued). "Importantly, the adoptive transfer of bone marrow from G6PD mutant mice to WT mice protected against diet-induced obesity and insulin resistance." (PMID 39061889, 2024). "G6PD mutant mice were protected from diet-induced obesity and insulin resistance." (PMID 39061889, 2024). "G6PD is the common player in glycolysis, gluconeogenesis, PPP, and lipid metabolism; also, overexpression of G6PD activity is associated with lipid dysregulation, insulin resistance, increased body weight, and obesity." (PMID 36992836, 2023). "Obesity and other behavioral factors may also affect tumor microenvironment, and G6PD and PLPP2 were also overexpressed in normal tissues form patients with advanced stage ccRCC in the TCGA dataset." (PMID 30603059, 2018). "Through the bioinformatics analysis, we identified HSD11B1, RXRG, G6PD, and PIK3R1 as core genes for the interplay between Crataegus pinnatifida and the obesity-related gut microbiota in obesity regulation." (PMID 41032481, 2025). "Branched chain amino acid (BCAA) supplementation was shown to decrease preadipocyte G6PD expression and NADPH levels to prevent obesity." (PMID 39061889, 2024). "It was recently demonstrated that abnormal activation of G6PD increases cellular nicotinamide adenine dinucleotide phosphate (NADPH), resulting in lipid dysregulation in obesity." (PMID 30544847, 2018). "Anti-obesity effects of YH have been verified in animals and humans, but the inhibition of G6PD and ME has not." (PMID 37761175, 2023). "First, glucose-6-phosphate dehydrogenase (G6PD), the initial enzyme of the oxidative branch of the PPP, is highly expressed in ATMs from obese compared with lean mice, and its levels in human adipose tissue correlate with several parameters of obesity." (PMID 34876704, 2022).
glioma (31 papers, 2016 to 2025). A benign or malignant brain and spinal cord tumor that arises from glial cells (astrocytes, oligodendrocytes, ependymal cells). "The G6PD gene is significantly overexpressed in a variety of tumor cells, including gliomas, and the activity of G6PD and expression is strongly correlated with tumor cell proliferation and poor patient outcomes." (PMID 41009654, 2025). "In order to explore the m6A modification of glucose-6-phosphate dehydrogenase (G6PD) in the carcinogenesis of glioma, ALKBH5 was upregulated, which stimulated glioma cells to proliferate." (PMID 35625706, 2022). "ALKBH5 has been found to be highly expressed in glioma and can eliminate the m6A methylation of G6PD through ALKBH5, improving the proliferation ability of glioma cells." (PMID 35688823, 2022). "Recently, it was reported that acute acidic treatment (pH 6.8 for 36 hours) increased the de novo purine nucleotide biosynthesis activity in glioma stem cells by upregulating glucose-6-phosphate dehydrogenase (G6PD) or G6PD expression." (PMID 35414794, 2022). "By analyzing relevant genes in the TCGA and Chinese Glioma Genome Atlas, we found that the expression of G6PD and H6PD, the two genes encoding glucose-6 phosphate dehydrogenase, was increased in glioma patients, particularly H6PD." (PMID 33723244, 2021). "In this study, we aim to investigate how HSPB activates G6PD in response to stressed conditions and its clinical relevance to glioma." (PMID 27711253, 2016). "HSPB1 activatedG6PD, the first and rate-limiting enzyme of pentose phosphate pathway, through enhancing SIRT2-mediated deacetylation of G6PD, hence protected glioma cells from oxidative stress and DNA damage." (PMID 27711253, 2016). "Some studies have reported that G6PD is upregulated in gliomas, and it might be related to poor prognosis." (PMID 40166471, 2025). "In addition, upregulated ALKBH5 demethylated G6PD mRNA and enhanced the stability and expression of G6PD in glioma, which activated the pentose phosphate pathway and stimulated the proliferation of glioma cells." (PMID 40001461, 2025). "Dysregulated G6PD activation promotes cell proliferation in various cancers including glioma." (PMID 39330272, 2024). "In addition, ALKBH5 catalyzes the G6PD mRNA demethylation and promotes G6PD translation, thus participating in glioma cells’metabolism of energy." (PMID 38102645, 2023). "HSP27 promotes glioma cell proliferation through SIRT2-mediated G6PD activation." (PMID 36639654, 2023). "HSPB1 enhanced SIRT2-mediated G6PD activation and promoted glioma cell proliferation." (PMID 36566214, 2022). "A negative association between G6PD expression and survival in patients with low-grade glioma was discovered." (PMID 36142793, 2022). "Key metabolic enzymes, such as H6PD or G6PD, may be potential targets for improving immune therapies and outcomes for glioma patients." (PMID 33723244, 2021). "HSPB1 also enhances proliferation via SIRT2-mediated G6PD activation in glioma cells." (PMID 32733879, 2020). "G6PD activity is increased in several types of cancers, including bladder, breast, endometrial, esophageal, prostate, gastric, renal, hepatic, colorectal, cervical, lung, and ovarian cancers, glioblastomas and leukemia, as well as gliomas." (PMID 31500396, 2019). "Besides, it is probable that combined treatment of glioma with SIRT2 or G6PD inhibitor would enhance anti-cancer effect of alkylating agent." (PMID 27711253, 2016). "Together, these data indicate that HSPB1 sustains G6PD activity in glioma cells." (PMID 27711253, 2016). "This study suggests that Chr-A markedly reduces the expression levels of GLS, GDH1, HK2 and G6PD in U87 and U251 glioma cells, which support the significant metabolic pathways identified through AFADESI-MSI, suggesting that these key enzymes might be potential targets for Chr-A." (PMID 39330272, 2024).